BTBD16 (BTB domain containing 16)
Synonyms: C10orf87; FLJ25359; Em:AC061711.1
Tractability: No criterion of Open Targets' tractability assessment is met for any kind of drug.
Gene: Protein-coding gene on chromosome 10 (122,271,296 to 122,338,159, forward strand). Ensembl gene ENSG00000138152.
Subcellular location (Human Protein Atlas): Nucleoli; Cytosol
Genetic constraint (gnomAD): Loss-of-function variants: 58 observed, 57.91 expected, observed/expected ratio (o/e) 1, 90% interval 0.81 to 1.25. The upper end of that interval is the gene's LOEUF score, 1.25, which puts it in group 5 of 6, group 1 being the genes least tolerant of losing a copy. Missense variants: 554 observed, 558.97 expected, observed/expected ratio (o/e) 0.99, 90% interval 0.92 to 1.06. Synonymous variants: 214 observed, 220.94 expected, observed/expected ratio (o/e) 0.97, 90% interval 0.87 to 1.09.
Homologues: Orthologues: chimpanzee BTBD16 (98% identical), macaque BTBD16 (91% identical), guinea pig BTBD16 (73% identical), pig BTBD16 (72% identical), dog BTBD16 (72% identical), rabbit BTBD16 (72% identical), mouse Btbd16 (70% identical), rat Btbd16 (69% identical), zebrafish btbd16 (34% identical), Drosophila melanogaster gcl (17% identical), Caenorhabditis elegans gcl-1 (14% identical). Paralogues in human: GMCL2 (20% identical), GMCL1 (20% identical), C10orf120 (10% identical).
Diseases named in the same sentence as BTBD16 in open-access papers:
BTBD16 is named in the same sentence as 9 diseases in open-access papers, as found by Europe PMC text mining. Sharing a sentence is not in itself a finding about the gene and the disease. The quoted sentences say what the papers report.
bladder cancer (1 paper, 2020). "The remaining 5 genes have not been found to be associated with the prognosis of bladder cancer (BTBD16, OLFML2B, PRRX1, SPINK4, and SPON2)." (PMID 33204728, 2020).
thyroid tumor (1 paper, 2023). A benign or malignant neoplasm affecting the thyroid gland. "On the other hand, the lack of expression of BTBD16 in thyroid tumor tissue would mean certain implications, but we have not found sufficient bibliographic evidence to conclude its role in TC." (PMID 37175550, 2023).
cancer (2 papers, 2018 to 2022). A tumor composed of atypical neoplastic, often pleomorphic cells that invade other tissues. "Consistent with the literature, the results of the present study showed fusion of the FGFR2 gene with nine different partners, namely, TACC2, BICC1, BTBD16, WAC, HFM1, HOOK1, INPP5F, C10orf90, and WDR11, in five different types of cancer." (PMID 35342406, 2022).
tumor (1 paper, 2023). "Immunohistochemistry (IHC) staining for BTBD16, EpCAM, FOXM1, AGXT and JMJD1C was carried out in normal and tumor thyroid tissue samples (three patient biopsies available), belonging to two NMTC families: NMTC_1 and NMTC_4." (PMID 37175550, 2023).
BTBD16 also shares sentences with these, for which no sentence is quoted: age-related macular degeneration (1 paper); benign tumors (1); cognitive decline (1); gastric cancer (1); memory impairment (1).